BCAT1 (branched chain amino acid transaminase 1)
Diseases named in the same sentence as BCAT1 in open-access papers (continued):
Sharing a sentence is not in itself a finding about the gene and the disease.
leukemia (28 papers, 2016 to 2025). A malignant (clonal) hematologic disorder, involving hematopoietic stem cells and characterized by the presence of primitive or atypical myeloid or lymphoid cells in the bone marrow and the blood. "Accordingly, knockdown of BCAT1 in leukaemia cells caused αKG accumulation leading to demethylases protein degradation and abrogated leukaemia-initiating potential." (PMID 35223487, 2022). "In leukemia cells, overexpression of BCAT1 decreases the intracellular 2-KG and causes DNA hypermethylation through inactivation of 2-KG-dependent enzymes and especially TET (ten-eleven translocation family of DNA demethylases)." (PMID 35409380, 2022). "In hematologic malignancies, Branched-chain Amino Acid Transaminase 1 inhibitors have been found to effectively inhibit the proliferation of Enhancer Of Zeste Homolog 2-deficient leukemia-initiating cells (EZH2-deficient leukemia-initiating cells), both in vitro and in vivo." (PMID 39605897, 2024). "Moreover, high BCAT1 expression was associated with the enrichment of leukemia stem-cell signature genes, and BCAT1 expression increased upon AML recurrence." (PMID 36979633, 2023). "In addition, studies on EZH2-deficient leukaemia found that BCAT1 was abnormally activated in EZH2-deficient cancer-initiating cells." (PMID 36119495, 2022). "Notably, BCAT1 expression has been associated with the outcome of leukemia." (PMID 40507232, 2025). "Accordingly, BCAT1 knockdown induces HIFα protein degradation, resulting in decreased leukemia-progression ability." (PMID 40282531, 2025). "Studies have shown multiple ways in which leukemia cells maintain abnormal elevation of BCAT1 expression to meet their needs." (PMID 40507232, 2025). "AML LSCs with BCAT1 knockdown also demonstrated poor leukemia-initiating potential when transplanted into NSG mice." (PMID 40282531, 2025). "The lentiviral knockdown of BCAT1 in leukemia stem cells (LSC) unsurprisingly led to an accumulation of α-KG, impairing LSC survival." (PMID 40282531, 2025). "In primary leukemia cells, BCAT1 actively breaks down BCAAs into branched-chain α-keto acids using α-KG, supplying key substrates for the tricarboxylic acid cycle and the synthesis of non-essential amino acids." (PMID 40438606, 2025). "Of note, BCAT1 is often overexpressed in leukemia cells and potentially also in other tumor cells, making the use of Leu7 for quantitative immunopeptidomics even more problematic." (PMID 39835134, 2024). "BCAT1 regulates gene epigenetics by restricting intracellular αKG to stabilize the HIF1α protein required for the maintenance of leukemia stem cells." (PMID 38028625, 2023). "Overexpression of BCAT1 in leukaemia stem cells reduces intracellular α-ketoglutarate (αKG), and DNA demethylase inactivation leads to DNA hypermethylation." (PMID 38028625, 2023). "Consistently, ectopic overexpression of Bcat1 in P2x1 knockdown AML cells decreased the leukemia cell frequencies in the peripheral blood and overall survival of recipient mice." (PMID 36418376, 2023). "We also measured the Bcat1 mRNA levels in WT, P2x1-null, Pbx3-overexpressing WT or P2x1-null leukemia cells and showed that the Bcat1 mRNA level was significantly downregulated in P2x1-null AML cells, while increased in Pbx3-overexpressing leukemic cells." (PMID 36418376, 2023). "In human AML, the BCAA pathway is enriched, and BCAT1 expression is elevated in leukemia stem cells." (PMID 35011702, 2022). "Conversely, overexpression of BCAT1 in leukemia cells reduced intracellular α-ketoglutarate levels and led to DNA hypermethylation via α-ketoglutarate-dependent ten–eleven translocation (TET) DNA demethylase activity." (PMID 35011702, 2022). "BCAT1 depletion in leukemia cells leads to the accumulation of α-ketoglutarate, resulting in enhanced Egl nine homolog 1 (EGLN1)-mediated HIF1α degradation." (PMID 35011702, 2022). "Proteomic analysis in acute myeloid leukemia (AML) found enrichment for BCAT1 in leukemia stem cells." (PMID 34109280, 2021).
leukemia (continued). "Patients with high levels of BCAT1 showed enrichment for leukemia stem cell signatures and relapsed patients present with an increase in BCAT1 levels." (PMID 34094959, 2021). "BCAT1 reactivation along with NRASG12D mutations can sustain intracellular BCAA pools, resulting in enhanced mTOR signaling in EZH2-deficient leukemia cells." (PMID 32448308, 2020). "In recent years, branched-chain AA aminotransferase 1 (BCAT1) was discovered to be involved in the progression of glioma, ovarian cancer, liver cancer, breast cancer, and leukemia, but less in CSCs." (PMID 31885621, 2019). "For instance, BCAT1 exerts its oncogenic function through BCAA production of leukemia by activating mTOR signaling." (PMID 29802157, 2018). "Interestingly, mice receiving Bcat1 KO ΔE-NOTCH1 GFP+ cells, although developing leukemia, showed a delay in succumbing to leukemia with respect to mice receiving Bcat1 WT ΔE-NOTCH1 GFP+ cells." (PMID 38928249, 2024). "Depleting BCAT1 impaired the growth and leukemia-initiating potential of AML cells." (PMID 36979633, 2023). "Activated BCAT1 cooperates with increased Glu to promote transamination of BCKA and maintain cellular BCAA pool levels, thereby affecting the development of EZH2-deficient leukemia." (PMID 36119495, 2022). "Depletion of BCAT1 results in α-KG accumulation in leukemia stem cells 47, which is consistent without observation that elevated expression of BCAT1 in metastatic A549 cells causes α-KG restriction." (PMID 34646394, 2021). "Similarly, in EZH2 inactivated leukemia stem cells (LSC), the combined effect of the loss of EZH2 and NRAS enhance BCAT1-mediated BCAA metabolism and upregulated the expression of genes involved in TCA (e.g., IDH)." (PMID 32448308, 2020). "Targeting BCAT1 will become a new target for stem cell therapy in leukemia." (PMID 31885621, 2019). "BCAT1 has been implicated in leukemia stem cell (LSC) metabolism as its overexpression decreased intracellular αKG levels and caused DNA hypermethylation through altered TET activity; AML with high levels of BCAT1 displayed a DNA hypermethylation phenotype similar to cases carrying a mutant IDH." (PMID 33946220, 2021). "EZH2 inactivation leads to BCAT1 overactivation, enhancing BCAA metabolism and mTOR signaling, which together drive the transformation of myeloproliferative neoplasms into leukemia." (PMID 40438606, 2025). "By employing proteomic analysis, it was uncovered that BCAT1 is overexpressed, and the BCAA pathway is enriched in leukemia stem cells." (PMID 36979633, 2023). "Critically, inhibition of either BCAT1 or mTOR is selectively detrimental to EZH2-null cells and prevents the transition of myeloproliferative neoplasms to leukemia." (PMID 34109280, 2021). "Our preliminary results indicate that Bcat1 may be a NOTCH1 target and that Bcat1 expression increases following leukemia development." (PMID 38928249, 2024). "In Acute Myeloid Leukemia (AML) stem cells, the α-KG level is restricted by the branched-chain amino acid transaminase 1 (BCAT1), which is overexpressed in leukemia stem cells and transfers α-amino groups from BCAAs to α-KG, resulting in α-KG instability to maintain leukemia stem-cell function." (PMID 35004688, 2021). "BCAT1 is generally low or not expressed in hematopoietic cells and exogenous expression of BCAT1 mimics the effects of the loss of EZH2 on leukemia initiating cells." (PMID 33329600, 2020). "Thus, we thought Bcat1−/− NOTCH1-T tumors could manifest distinct metabolic features to Bcat1+/+ NOTCH1-T tumors, somewhat mimicking metabolic heterogeneity found in human disease and may be an interesting model to include to evaluate our metabolic classifier for leukemia." (PMID 38928249, 2024).
acute myeloid leukemia (24 papers, 2019 to 2025). Acute myeloid leukemia (AML) is a group of neoplasms arising from precursor cells committed to the myeloid cell-line differentiation. "At the level of key metabolic enzyme targeting, curcumin inhibits the mRNA expression of BCAT1 in human myeloid leukemia cell lines and bone marrow mononuclear cells derived from acute myeloid leukemia (AML) patients." (PMID 41515171, 2025). "In acute myeloid leukemia, BCAT1 overexpression promotes cancer stem cell proliferation by regulating amino acid metabolism." (PMID 38309289, 2024). "As the overexpression of BCAT1 is found in LSCs in TET2/Isocitrate dehydrogenase (IDH) wild-type acute myeloid leukemia, BCAT1 has been proposed as a driver of LSC self-renewal through its reduction of TET2 activity." (PMID 34830976, 2021). "Notably, increased glutamate levels in EZH2-mutant acute myelogenous leukemia drive BCAA production by BCAT1 to support mTORC1 and to restrict αKG levels." (PMID 40924473, 2025). "Notably, increased glutamate levels in EZH2-mutant acute myelogenous leukemia drive BCAA production by BCAT1 to support mTORC1 and also to restrict aKG levels." (PMID 38854072, 2024). "In our study, conspicuous positive associations between BCAT1 expression and the five MMR genes can be detected in quite a few cancers, particularly for HNSCC, acute myeloid leukemia, LIHC, ovarian serous cystadenocarcinoma (OV), and uterine corpus endometrial carcinoma (UCEC)." (PMID 34984849, 2022). "Besides acute myeloid leukemia, BCAT1 is also activated in the blast crisis of chronic myelocytic leukemia (CML)." (PMID 33511116, 2020). "For example, reduced levels of α-KG due to BCAA transaminase 1 (BCAT1) overexpression in acute myeloid leukemia (AML) cells were found to inhibit TET demethylase activity, thereby inducing DNA hypermethylation, which promoted AML cell survival and lead to decreased clinical outcome." (PMID 30809153, 2019). "In acute myeloid leukemia (AML), for instance, high BCAT1 in leukemic stem cells depletes α-KG and induces a DNA hypermethylation profile akin to IDH-mutant leukemias." (PMID 41502503, 2025). "In acute myeloid leukemia (AML) cells of Ezh2−/− NRasG12D mice, the overexpression of BCAT1 is responsible for converting BCKAs back to BCAAs." (PMID 40507232, 2025). "Inhibiting BCAT1 also elevates αKG levels, impairing acute myeloid leukemia (AML) stem cell function." (PMID 38305803, 2024). "Emerging studies have shown that the BCAA metabolic enzymes BCAT1 and BCAT2 are aberrantly activated and functionally required for malignant tumors such as chronic myeloid leukemia, acute myeloid leukemia, and PDAC." (PMID 36341436, 2022). "Thus, BCAT1 is an important metabolic enzyme for α-KG generation in acute myeloid leukemia (AML) progression." (PMID 33511116, 2020). "Endogenous metabolic networks may determine αKG availability: the branched-chain amino acid transaminase 1 (BCAT1) enzyme, which transaminates αKG to initiate catabolism of valine, leucine, and isoleucine, constrains αKG pools in acute myelogenous leukemia." (PMID 36581208, 2023). "Therefore, the aim of this study was to further characterise the BCAT1 CXXC motif and evaluate its role in acute myeloid leukaemia." (PMID 35453368, 2022). "In acute myeloid leukemia (AML), METTL16 drives tumor development by promoting the expression of branched-chain amino acid (BCAA) transaminases BCAT1 and BCAT2, reprogramming BCAA metabolism." (PMID 41256854, 2025).
colorectal cancer (24 papers, 2008 to 2024). A primary or metastatic malignant neoplasm that affects the colon or rectum. "In addition to clinical trials involving hepatocellular carcinoma, the value of BCAT1 as a diagnostic marker was recently tested in patients with colorectal cancer, alongside the ikaros family zinc finger 1 (IKZF1) gene." (PMID 29211698, 2018). "In colorectal cancer, researchers found significantly higher levels of BCAT1 methylation in circulating tumor DNA (ctDNA) than in normal controls." (PMID 39324007, 2024). "The DNA methylation level of two biomarkers used for the detection of recurrence of colorectal cancer, BCAT1 and IKZF1, was analyzed using ddPCR with the 4Plex assay for normalization." (PMID 37710283, 2023). "BCAT1 is abnormally expressed in colorectal cancer (CRC) with significantly higher levels of cyclic tumor DNA (ctDNA) methylation, which can be used for CRC diagnosis with high sensitivity and specificity." (PMID 38028625, 2023). "In a previous study, 10 mM Gabapentin was found to inhibit the growth of the HCT116 colorectal cancer cell line, for which BCAT1 expression is naturally low." (PMID 35453368, 2022). "Similar to our results, BCAT1 is hypomethylated in some patients with colorectal cancer, and is being investigated as a peripheral biomarker." (PMID 30265706, 2018). "BCAT1 was one of the top up-regulated genes in AA colorectal cancer patients-derived samples, as compared to samples from CA colorectal cancer patients." (PMID 28931403, 2017). "In colorectal cancer immuno-histochemical analysis of BCAT1 protein showed significantly higher levels of expression in tumor tissues with distant metastasis compared to those without and was shown to be highly predictive of distant metastasis." (PMID 22355333, 2012). "Moreover, it was found that long non-coding RNA (lncRNA) TMPO-AS1 can upregulate the expression of BCAT1 through miR-98-5p, thereby promoting the progression of colorectal cancer cells." (PMID 38028625, 2023). "Additionally, hsa-miR-98–5p has been proved to be a target of lncRNA TMPO-AS1, inhibiting the progression of colorectal cancer cells by downregulating the expression of branched chain amino acid transaminase 1 (BCAT1)." (PMID 35795552, 2022). "Moreover, BCAA supplementation and BCAT1 status were tested in clinical trials for hepatocellular carcinoma and colorectal cancer." (PMID 29211698, 2018). "Differently methylated regions within markers such as BCAT1, SEPT9 and IKZF1 have previously been shown to have ignorable levels of methylation in WBCs and high levels in colonoscopy-confirmed patients with colorectal cancer." (PMID 37438612, 2023). "The biomarkers used for the proof-of-principle analysis, DNA methylation of BCAT1 and IKZF1, have previously been used to detect recurrence of colorectal cancer in plasma samples." (PMID 37710283, 2023). "Cell-free circulating tumour-derived DNA (ctDNA) can be detected by testing for methylated BCAT1 and IKZF1 DNA, which has proven sensitivity for colorectal cancer (CRC)." (PMID 29796114, 2018). "For a number of cancers it has been possible to identify particular genes that are methylated with high frequency, e.g., GSTP1 in prostate cancer, SHOX2 in lung cancer, SEPT9, NRDG4, RASSF1A, THBD, BCAT1 and IKZF1 in colorectal cancer (CRC)." (PMID 27983717, 2016). "Specific genes, such as BCAT1 and IKZF1, are methylated with high frequency in colorectal cancer (CRC) tissue compared to normal colon tissue specimens." (PMID 26445409, 2015). "The genes BCAT1, GGH and SERPINB9 have been correlated to clinical outcome in other types of cancer, such as colorectal cancer, neuroendocrine cancer, large cell lymphoma and melanoma." (PMID 18778486, 2008).
colorectal cancer (continued). "A similar sensitivity was observed in this study, with methylation of BCAT1 and/or IKZF1 detected in plasma from 6/10 (60%) stage IV patients, demonstrating the successful use of the combination of CNA and EpiTect kits for detection of these biomarkers in blood from colorectal cancer patients." (PMID 37710283, 2023). "DMRs residing in four genes, BCAT1, GRASP, IKZF1 and IRF4, exhibited low positivity, 3.5% to 7%, in the plasma of colonoscopy-confirmed healthy subjects, with the sensitivity for detection of ctDNA in colonoscopy-confirmed patients with colorectal cancer being 65%, 54.5%, 67.6% and 59% respectively." (PMID 27983717, 2016).
lung cancer (19 papers, 2018 to 2025). A malignant neoplasm involving the lung. "Consistent with a role for these Wnt factors in BCAT1-associated enhancement of lung cancer cell migration, a previous study reported that BCAT1 promoted lung cancer cell invasion and proliferation via activating Wnt signaling." (PMID 34646394, 2021). "Analysis of transcriptomic data available in the TCGA database revealed that increased BCAT1 transcription is associated with poor overall survival of lung cancer patients." (PMID 34646394, 2021). "Taken together, it appears that overexpression of BCAT1 may be a causal event driving lung cancer cell metastasis, and reducing BCAT1 expression suppressed cancer cell migration and metastasis." (PMID 34646394, 2021). "Similarly, loss of H3K9 methylation at the BCAT1 gene promoter coincides with increased BCAT1 expression in tyrosine kinase inhibitor (TKI)-resistant epidermal growth factor receptor (EGFR)-mutant lung cancer cells." (PMID 34109280, 2021). "Pan-cancer biological analyses show that the infiltration levels of CD4+ T cells, CD8+ T cells, B cells, neutrophils, and macrophages in lung cancer, colorectal cancer, and head and neck squamous cell carcinoma are correlated with the expression of BCAT1." (PMID 40438606, 2025). "WQQ-345 was further demonstrated to exhibit both in vitro and in vivo antitumor activity against TKI-resistant lung cancer with high BCAT1 expression." (PMID 40005214, 2025). "Consistent with these preclinical findings, BCAT1 and several key downstream glycolysis genes are upregulated in primary lung cancer, with even higher expression in samples from patients who eventually relapsed." (PMID 39143065, 2024). "To assess the clinical relevance of BCAT1 in lung cancer, we analyzed specimens from a cohort of patients with primary lung adenocarcinoma (LUAD) and samples of normal lung tissues using the GSE31210 dataset from the Gene Expression Omnibus (GEO) database." (PMID 39143065, 2024). "In summary, this study elucidates the significance of BCAT1-mediated BCAA metabolic reprogramming in enhancing cell survival and TKI resistance in NSCLC, which provided extensive evidence for directly targeting BCAT1 as a therapeutic strategy for lung cancer." (PMID 39143065, 2024). "Overexpression of BCAT1 in lung cancer cells led to a dramatic downregulation of α-KG and resulted in activation of SOX2." (PMID 37460470, 2023). "G9a and SUV39H1 are histone modifiers that catalyze di- and tri-methylation of histone H3 (H3K9) at the promoter of the BCAT1 gene, resulting in BCAT1 downregulation in lung cancer cells." (PMID 36358687, 2022). "To explore a possible causal relationship between overexpression of BCAT1 and increased SOX2 expression in metastatic lung cancer cells, we knocked down BCAT1 in these cells and observed consequent reduction of SOX2 at both the mRNA and protein level." (PMID 34646394, 2021). "We found that high expression of BCAT1 negatively regulates miR200c expression in metastatic lung cancer cells, suggesting a possible post-transcriptional influence of BCAT1 on SOX2 expression." (PMID 34646394, 2021). "To explore the potential role of BCAT1 in lung cancer cell metastasis, we first examined cell migration." (PMID 34646394, 2021). "To gain additional insights on the potential role of BCAT1 dysregulation in lung cancer, we utilized TCGA data and performed Kaplan-Meier survival analysis based on mRNA expression of BCAT1." (PMID 34646394, 2021). "In this study, we demonstrate that overexpression of BCAT1 plays an important role in lung cancer cell migration and metastasis." (PMID 34646394, 2021). "In conclusion, we found that BCAT1 expression was upregulated in metastatic lung cancer cells, regulates their migration and metastasis, and is associated with poor prognosis." (PMID 34646394, 2021).